IL6 (interleukin 6)
Diseases named in the same sentence as IL6 in open-access papers (continued):
Sharing a sentence is not in itself a finding about the gene and the disease.
COVID-19 (continued). "In COVID-19 patients, ROC analysis regarding the detection of infiltrate above the median compared to infiltrate below the median showed satisfying predictive values for CRP (AUC = 0.82, p < 0.001) and IL-6 (AUC = 0.78, p < 0.001)." (PMID 37733154, 2023). "The hyper-proinflammatory cytokine storm, including interleukin-6, nuclear factor kappa B (NF-κB), and TNF-α released from SARS-CoV-2-infected macrophages and monocytes, results in multi-organ injury/failure and the development of severe COVID-19." (PMID 36674700, 2023). "Additional studies have also revealed that patients with severe COVID-19 have a significantly elevated cytokine profile of IL-2, IL-6, IL-7, IL-10, IP-10, MCP-1, TNF-α, macrophage inflammatory protein 1 alpha, and granulocyte-CSF compared to patients with mild to moderate COVID-19." (PMID 37457959, 2023). "This review discusses the pathophysiology between COVID-19 and HGF, IL-6, and D-dimer." (PMID 37504277, 2023). "Recent studies have linked laboratory measures of hyperinflammation such as macrophage chemoattractant protein 1 (MCP-1), C-reactive protein (CRP) and interleukin-6 (IL-6), ferritin and procalcitonin (PCT) as strong predictors of disease severity in hospitalized patients with COVID-19." (PMID 37744227, 2023). "COVID-19 hyper-inflammatory subpopulation, compared to pauci-inflammatory, had higher levels of IL-10 (median [IQR] 61.4 [42.0–109.4] vs 13.0 [5.0–24.9], P: < 0.001), IL-6 (48.1 [22.3–82.6] vs 9.1 [0.1–30.4], P: < 0.001), among others." (PMID 36814234, 2023). "Herein we showed for the first time that IL-6 and NLR could predict the severity of the disease in COVID-19 patients with DM." (PMID 37834356, 2023). "Notably, among cytokines, IL-6, TNF-α and IL-1β have been identified as the key targets of COVID-19-induced PF." (PMID 37601070, 2023). "Pathway analysis identified several immunity-related genes that may link ADHD to COVID-19, including CRP, OXT, IL6, PON1, AR, TNFSF12, and IL10." (PMID 38066446, 2023). "Indeed, IL-6, IL-1β, and tumor necrosis factor alpha (TNF-α) were found to be significantly elevated in COVID-19 patients." (PMID 37762435, 2023). "In the present retrospective study, low-cost markers such as IL-6 and the NLR could be used as potential predictors of the outcome in mechanically ventilated patients with severe COVID-19 admitted to the ICU living at high altitude." (PMID 36675573, 2023). "Moreover, it was revealed that children with PIMS-TS have higher levels of IL-6, IFN-, TNF-, and CXCL10 (chemokine “C-X-C motif” ligand) than children with acute COVID-19." (PMID 36839601, 2023). "The clinical chemistry data showed a significant elevation of inflammatory biomarkers including C-reactive protein (CRP) and procalcitonin (PCT), but not interleukin 6 (IL-6) in the COVID-19 group compared to the non-COVID-19 group." (PMID 37386635, 2023). "We observed increased serum levels of IL-1α prior to a rise in IL-6 levels in the sera of severely affected COVID-19 patients, independent of ECMO therapy." (PMID 37834869, 2023). "However, SARS-CoV-2 infection has been shown to suppress type I IFN antiviral responses (e.g., IFN-α and IFN-β) and elevate the production of inflammatory cytokines (e.g., IL-1β, IL-6, and TNF-α) in blood and lung samples from COVID-19 patients." (PMID 36883057, 2023). "A retrospective study of COVID-19 patients found that elevated serum ferritin and IL-6 correlated with nonsurvivors." (PMID 37686271, 2023). "Moreover, Proinflammatory cytokines like interleukin (IL)-1β, IL-17, IL-6, also tumour necrosis factor-α (TNF-α) that are involved in AD development are significantly elevated in cerebrospinal fluid of COVID-19 patients." (PMID 38259635, 2023). "First, we confirm previously reported data showing that COVID-19 patients show increased plasma levels of IL-1β and IL-6 compared to pneumonia patients non-SARS-CoV-2 related." (PMID 37986089, 2023).
COVID-19 (continued). "Stratified analysis established that pre-pandemic plasma IL-6 levels were elevated in participants with chronic fatigue in the COVID-19-negative group." (PMID 36995412, 2023). "PAL was also associated with modulation of the peripheral frequency of Treg cells and the expression of PD-1 in CD8+ T cells, although it abrogated the statistical effect in the analysis of TNF-α and IL-6 production by LPS- and PMA-stimulated PBMC of post-COVID-19 patients." (PMID 37753077, 2023). "A possible mechanism that explains this association is that the anti-NP antibody via the Fc-receptor induces the production of the main pro-inflammatory cytokine, IL-6, in lung alveoli infected with SARS-CoV-2 due to the cytokine storm observed in COVID-19, potentiating the disease severity." (PMID 37876932, 2023). "IL-1, IL-6, IP-10, TNF, IFNγ, MIP and VEGF are elevated in COVID-19 patients." (PMID 37298597, 2023). "Immune dysregulation may be influenced by IL-6, as suggested by the correlation between its levels and SARS-CoV-2 viremia and COVID-19 severity." (PMID 36941580, 2023). "Similarly, a study found that IL-6 and TNF-α elevation was sustained in subjects that experienced symptoms at approximately 120 days following COVID-19." (PMID 37565145, 2023). "Moreover, inflammatory markers including C-reactive protein, ferritin, interleukin (IL)-6, IP-10, MCP1, MIP1A, TNF-α, and vWF all were elevated in COVID-19 patients." (PMID 37854057, 2023). "In COVID-19 patients, 8-isoprostaglandin F2 alpha levels, considered as a marker of oxidative tissue damage, were elevated, and in a recent study, COVID-19 patients showed significantly higher values of hydrogen peroxide (H2O2) and NADPH oxidase 2 (NOX2) activity in serum, as well as TNF-α and IL-6." (PMID 37569625, 2023). "Moreover, COVID-19 convalescents were noted to contain peripheral blood autoantibodies against various cytokines (IFN-α, IFN-ω, IFN-γ, IL-1β, IL-6, IL-10, IL-17, IL-21, and GM-CSF) and chemokines (CCL2, CXCL1, CXCL7, CXCL13, and CXCL16)." (PMID 38179278, 2023). "A systematic review of 52 articles involving 6320 COVID-19-positive patients revealed that elevated levels of neutrophil count, WBC, prolonged PT, ESR, D-dimer, fibrinogen, procalcitonin, IL-6, and IL-10 can more significantly progress to a more serious form of COVID-19 infection." (PMID 37235308, 2023). "Studies have shown that IL-6 transcript levels in COVID-19 patients did not change significantly compared to controls that confirm this theory." (PMID 37654571, 2023). "Due to IL-6’s independent correlation with cancer and COVID-19 infection, as well as its close relation to CRP, IL-6 should be considered a potential prognostic indicator for cancer patients with COVID-19 illness, but further trials are needed." (PMID 38127882, 2023). "COVID-19-depleted carbohydrate metabolites and neurotransmitters had a positive correlation with reduced levels of cytokines (e.g., CCL22, IL-12 and IL-13) while negatively correlated with increased levels of inflammatory cytokines (e.g., IL-6 and IL-10)." (PMID 37205106, 2023). "In support of this hypothesis, a recent study found that COVID-19 patients had reduced upregulation of CD80 on monocytes and abrogated release of IL-6, TNF, IL-1a and IL-1b in response to Candida albicans." (PMID 38169876, 2023). "The resulting increased systemic cytokine production contributes to the pathophysiology of severe COVID-19, including hypotension, ARDS, which might be treated with IL-6 antagonists, i.e., tocilizumab, sarilumab, and siltuximab." (PMID 37686271, 2023). "In our cohort of acutely ill patients with moderate to severe COVID-19 ARDS, the marked increase in serum catecholamine levels (particularly norepinephrine) correlated with the degree of systemic inflammation, expressed by CRP and IL-6." (PMID 36836097, 2023).
COVID-19 (continued). "As a whole, the findings imply that overexpression of hsa_circ_0000479 may affect the expression of IL-6 and RIG-I via sponging hsa-miR-149-5p in COVID-19." (PMID 37759744, 2023). "Several studies have shown that IL-1 controls the biosynthesis of IL-6, which is known to be one of the major negative prognostic factors in COVID-19." (PMID 37241099, 2023). "In the present study, COVID-19 samples were collected at three different time points of the disease course, and sera were used with the N protein in K-ML2 cell culture to clarify the enhancement of IL-6 production." (PMID 37896795, 2023). "Patterns of cytokine alterations in AP and COVID-19 were shown to be remarkably similar in a recent meta-analysis, with tumor necrosis factor-alpha (TNF-α), interleukin (IL)-6, IL-8, and IL-10 concentrations significantly higher in more severe forms than non-severe forms of the two diseases." (PMID 36834656, 2023). "In addition, we also enrolled a comparator population of non-COVID-19 patients admitted to the ICU (n = 106) and measured IL-6 levels using the Roche Elecsys assay." (PMID 37650680, 2023). "In summary, our work sheds light on the role of IL-6 in general chronic fatigue, but it does not support a specific role for IL-6 levels in the development of chronic fatigue following mild COVID-19." (PMID 36995412, 2023). "For example, the “IL6-JAK-STAT3 signaling” gene set was upregulated in both groups at both timepoints when compared to healthy controls, but also relatively upregulated at D1 in COVID-19 patients compared to non-COVID-19 sepsis patients." (PMID 37090709, 2023). "Importantly, macrophages are one of the main sources of proinflammatory cytokines such as IL-6 and TNF and were found to play a central role in the pathology of severe COVID-19." (PMID 37253946, 2023). "Increases in D-dimer, a protein fragment produced during dissolution of blood clots, together with the pro-inflammatory marker, C-reactive protein (CRP), ferritin, TNF-α, IL-1β, IL-6, and IL-13, as well as sPLA2-IIA activity, were also found in patients with COVID-19 compared to normal persons." (PMID 37189799, 2023). "Recently, COVID-19 patients were shown to have higher levels of Gal-3, TNF-α, IL-1β, and IL-6." (PMID 37112643, 2023). "A positive correlation was found between IL-6 and NLR and COVID-19 severity (r = 0.612; p <0.001)." (PMID 38099004, 2023). "Based on the clinical features of our patients, there were differences in age, BMI, total cholesterol, IL6, and adverse outcomes between COVID-19 patients with and without myocardial injury." (PMID 37564653, 2023). "The negative evolution of COVID-19 can be presumed by measuring the IL-6, CRP, lymphocytes, and NLR, which are strongly correlated." (PMID 36838284, 2023). "Besides IL-6, CRP and platelet and neutrophil counts also allowed to discriminate between death and discharge in patients hospitalized with severe COVID-19, but only during the first wave." (PMID 36817433, 2023). "It has been observed that the level of interleukin (IL)-1, IL-6, interferon (IFN)-γ, granulocyte-macrophage colony-stimulating factor, tumor necrosis factor (TNF) were significantly increased in patients with severe COVID-19." (PMID 37391394, 2023). "A protein–protein interaction network analysis identifies sIL2R, IL6, IP-10, IL-10 and MIG as the network path with the highest inflammation in MIS-C relative to COVID-19, indicating that there are two pathways mediated by NFkB and IFN-Υ leading to elevated IP-10 and MIG." (PMID 37685502, 2023). "Although it is not current practice at the Hospital del Mar study center, IL-6 levels above 35 pg/ml have been used elsewhere to ascertain the need for mechanical ventilation in COVID-19 patients." (PMID 36653401, 2023).
COVID-19 (continued). "Indeed, since SARS-CoV-2 infection can induce an inflammatory response with the hyperactivation of the immune system, we studied the possible correlations between inflammation markers such as IL-6 and ferritin and HE4 in COVID-19 patients." (PMID 37297598, 2023). "In line with our findings, several reports described the overproduction of IL-6, TNF-α, and IL-1β, leukopenia and coagulopathy, marked by platelet activation and high D-dimer levels, accounting for the development of the more severe forms of the COVID-19." (PMID 37283924, 2023). "Indeed, IL-6 and TNF-α are pro-inflammatory cytokines involved in the immunopathology of COVID-19; IL-6, in particular, can lead to macrophage activation syndrome and cytokine storm, the most serious complications of COVID-19." (PMID 37520439, 2023). "Furthermore, prophylactic administration of ivermectin suppressed the expression of pro-inflammatory cytokines (IL-6 and TNF) reported to be increased in severe cases of COVID-19." (PMID 37185581, 2023). "In addition, inflammatory markers such as IL-6 and CRP are also less expressed in COVID-19 patients receiving CP blood transfusion." (PMID 37483597, 2023). "TNFα but not IL-6 or IL-10 levels were increased in mild COVID-19 patients, compared to healthy controls." (PMID 36509969, 2023). "In the case of COVID-19, the cytokines involved in cytokine storm mainly include tumor necrosis factor-alpha (TNF-α), interleukin 1β (IL-1β), interleukin 6 (IL-6), interleukin 8 (IL-8), interleukin 10 (IL-10), interferon alpha (IFN-α), and granulocyte-macrophage colony-stimulating factor (GM-CSF)." (PMID 37841241, 2023). "Finally, miR-451a, which is known for targeting and inhibiting the IL-6/STAT3 axis, was found to be downregulated in COVID-19 patients." (PMID 36834984, 2023). "A previous study reported that IL-6 levels were significantly higher in severe COVID-19 cases than in non-severe cases (25.2 vs. 13.3 pg/mL; p < 0.001)." (PMID 37529051, 2023). "In addition, cluster 1 confirms the existence of the top ten potential anti-COVID-19 core targets (AKT1, TNF, HSP90AA1, IL-6, mTOR, EGFR, CASP3, HIF1A, MAPK3, and MAPK1); consequently, the results of the PPI and cluster network analyses are congruent." (PMID 36817449, 2023). "Peripheral insulin resistance is also induced by the inflammatory response and cytokine storm triggered by COVID-19, characterized by significant increases in the levels of inflammatory markers, such as tumor necrosis factor-alpha (TNF-alpha) and interleukin-6 (IL-6)." (PMID 37649125, 2023). "In conclusion, IL1-RA, IL-6, IFN-γ, G-CSF, CCL-7 and VEGF serum levels could prove helpful as biomarkers to assess disease severity and the need for intensive care in COVID-19 patients." (PMID 37917760, 2023). "We also calculated prevalence of fatigue in COVID-19-positive and COVID-19-negative participants stratified by high and low levels of pre-pandemic IL-6." (PMID 36995412, 2023). "A previous study has shown that increased levels of IL-6 are strongly associated with disease severity at admission and the need for ICU care in COVID-19 patients, regardless of age." (PMID 37081872, 2023). "It appears that the high and uncontrolled release of pro-inflammatory cytokines (such as IL-6, IL-1, TNF-⍺) in COVID-19, ie the cytokine storm, is one of the main mechanisms explaining the severity of the disease in elderly patients, causing acute respiratory distress syndrome and death." (PMID 37498909, 2023). "Results from the hamster challenge study demonstrated a strong anti-inflammatory potential of A64, as the mRNA expression of inflammatory cytokines such as IL-6, IL-17A, and TNF-α (all of which have been strongly correlated with COVID-19 severity) was significantly reduced." (PMID 37765142, 2023). "Indeed, previous studies have defined IL-6, IL-8/CXCL8 and, IP-10/CXCL10 as early prognostic parameters of COVID-19 severe disease." (PMID 36997530, 2023).
COVID-19 (continued). "BAL alveolar macrophages from severe COVID-19 patients (n = 23) were characterized by an increased production and release of several pro-inflammatory mediators, such as IL-1β, IL-6, CCL3 and CCL4 and increased expression of IL-1R and S100A8/9 proteins, compared to those from mild COVID-19 patients." (PMID 36941580, 2023). "Acute COVID-19 children had significantly elevated levels of cytokines, (Interferon (IFN)) IFNγ, Interleukins (IL)-2, TNFα, IL-1α, IL-1β, IFNα, IFNβ, IL-6, IL-12, IL-17A and Granulocyte-Colony Stimulating Factors (G-CSF) in comparison to convalescent COVID-19 and controls." (PMID 37013538, 2023). "In COVID-19, some validated scoring systems, such as the SCOPE score, which is based on biomarkers such as C-reactive protein (CRP), ferritin, D-dimer, and IL-6, demonstrated good prediction of the progression of COVID-19 pneumonia to severe respiratory failure or death within 14 days." (PMID 36675573, 2023). "Cytokine detection: Comparing cytokine levels quantification in laboratory controls and patients in the 4/6-day collection after study admission, it was seen that non-severe COVID-19 cases showed an increase in IL1β, IL-6, IL-10 and TNF." (PMID 37515295, 2023). "Patients with COVID-19 had substantially greater levels of ACE2, IL-6, TNF-α, glucose, total white blood cells (WBCs), neutrophils, NLR, platelets, mean corpuscular hemoglobin (MCH), and mean corpuscular hemoglobin concentration (MCHC) than the healthy participants." (PMID 37240319, 2023). "Theoretically, the monoclonal antibody against IL-6, tocilizumab, could have an anti-inflammatory effect in NASH, as it is effective against hyperinflammatory states of COVID-19, but it has also demonstrated liver enzyme elevations and DILI in a few cases." (PMID 37842470, 2023). "On the other hand, the blood test results that were considered in the final model were primarily taken in subjects admitted during the first waves of COVID-19, but currently, parameters such as IL6 and CRP are not routinely collected at admission." (PMID 36835788, 2023). "In the severe COVID-19 cohort, HIF signaling could likely be triggered by IL-6, IFNγ and growth factors (VEGF and/or EGF) as ligands of receptor tyrosine kinases." (PMID 37301958, 2023). "Increased serum IL-6 levels were found in non-surviving (n = 54) compared to surviving (n = 137) COVID-19 patients." (PMID 36941580, 2023). "IL-6 and TNF can contribute to the cytokine storm in COVID-19 patients." (PMID 37515272, 2023). "It is the condition for discussing the possible interest of evaluating type 1 IFN treatment in patients with severe COVID-19 who harbor type 1 IFN decline before the critical phase of the disease, eventually combined with anti-inflammatory drugs like dexamethasone and IL-6 inhibitors." (PMID 38077399, 2023). "In aggregated analysis, Eotaxin-3 and Eotaxin-1 levels decreased in COVID-19 patients; however, in sex-segregated analysis, Eotaxin-3, CCL5, IL-21, and IL6+CD4+ T cell levels were lower in female versus male HCW and this sex difference was maintained in female versus male COVID-19 patients." (PMID 37998327, 2023). "These include interleukin-1 (IL-1), IL-6, IL-18, IL-10, interferon gamma (IFN-γ) and tumor necrosis factor-alpha (TNF-α) secreted by T helper type 1 (TH1) and other cells during the inflammatory process of COVID-19." (PMID 37447302, 2023). "A similar time-dependent increase has been reported for IL-6, IL-8, IL-1β, and TNF-α in COVID-19." (PMID 38069209, 2023). "This SWCNT array is an ultrasensitive platform for detecting IL-6; however, the level of IL-6 in different pathological conditions is usually higher than the linear response range of the SWCNT/Au sensor, including that of COVID-19." (PMID 36679421, 2023). "Significantly elevated IL-6 levels were observed in non-survivor COVID-19 patients compared to survivor patients." (PMID 38068297, 2023). "Very few studies have investigated IL-6 and NLR cut-offs as predictors of COVID-19 severity." (PMID 38099004, 2023).